ZDHHC8 (zDHHC palmitoyltransferase 8)
Description:
Palmitoyltransferase that catalyzes the addition of palmitate onto various protein substrates and therefore functions in several unrelated biological processes (Probable). Through the palmitoylation of ABCA1 regulates the localization of the transporter to the plasma membrane and thereby regulates its function in cholesterol and phospholipid efflux (Probable). Could also pamitoylate the D(2) dopamine receptor DRD2 and regulate its stability and localization to the plasma membrane (Probable). Could also play a role in glutamatergic transmission (By similarity). (Microbial infection) Able to palmitoylate SARS coronavirus-2/SARS-CoV-2 spike protein following its synthesis in the endoplasmic reticulum (ER). In the infected cell, promotes spike biogenesis by protecting it from premature ER degradation, increases half-life and controls the lipid organization of its immediate membrane environment. Once the virus has formed, spike palmitoylation controls fusion with the target cell.
Synonyms: KIAA1292; ZDHHCL1; ZNF378; DHHC8
Tractability: Antibody: UniProt predicts a signal peptide or a membrane-spanning region. PROTAC: ubiquitination databases record sites on it.
Gene: Protein-coding gene on chromosome 22 (20,129,456 to 20,148,007, forward strand). Ensembl gene ENSG00000099904.
Subcellular location: Golgi apparatus membrane; Mitochondrion membrane
Subcellular location (Human Protein Atlas): Cytosol; Nucleoplasm
Pathways (Reactome):
Disease: Maturation of spike protein
Transport of small molecules: HDL assembly
Gene Ontology:
Molecular function: palmitoyltransferase activity; protein-cysteine S-palmitoyltransferase activity
Biological process: host-mediated activation of viral process; peptidyl-L-cysteine S-palmitoylation; positive regulation of cholesterol efflux; protein localization to plasma membrane; high-density lipoprotein particle assembly; positive regulation of protein localization to plasma membrane; regulation of postsynapse assembly
Cellular component: Golgi apparatus; Golgi membrane; cytosol; mitochondrial membrane; glutamatergic synapse; mitochondrion; postsynapse
Genetic constraint (gnomAD): Loss-of-function variants: 24 observed, 55.9 expected, observed/expected ratio (o/e) 0.43, 90% interval 0.31 to 0.6. The upper end of that interval is the gene's LOEUF score, 0.6, which puts it in group 2 of 6, group 1 being the genes least tolerant of losing a copy. Missense variants: 935 observed, 1,038.5 expected, observed/expected ratio (o/e) 0.9, 90% interval 0.85 to 0.95. Synonymous variants: 523 observed, 466.3 expected, observed/expected ratio (o/e) 1.12, 90% interval 1.04 to 1.21.
Homologues: Orthologues: chimpanzee ZDHHC8 (99% identical), macaque ZDHHC8 (94% identical), mouse Zdhhc8 (92% identical), guinea pig ZDHHC8 (91% identical), pig ZDHHC8 (89% identical), rabbit ZDHHC8 (88% identical), rat Zdhhc8 (87% identical), dog ZDHHC8 (85% identical), tropical clawed frog pgam5 (59% identical), zebrafish zdhhc8b (58% identical). Paralogues in human: ZDHHC5 (46% identical).
Diseases named in the same sentence as ZDHHC8 in open-access papers:
ZDHHC8 is named in the same sentence as 22 diseases in open-access papers, as found by Europe PMC text mining. Sharing a sentence is not in itself a finding about the gene and the disease. The quoted sentences say what the papers report.
schizophrenia (26 papers, 2005 to 2025). A major psychotic disorder characterized by abnormalities in the perception or expression of reality. "According to the literature, defects found in ZDHHC8 can be linked to susceptibility to schizophrenia." (PMID 37486921, 2023). "Another gene linked to schizophrenia is ZDHHC8 (Zinc Finger DHHC-Type Palmitoyltransferase 8), which is located on chromosome 6q24-q25." (PMID 37486921, 2023). "Significant associations between schizophrenia and small nucleotide polymorphisms in the ZDHHC8 gene, within the schizophrenia risk 22q11 microdeletion, have been identified in multiple populations but not in others." (PMID 34659801, 2021). "We also tested the PAT zDHHC8 for interaction with D2L, because its gene maps to a schizophrenia susceptibility locus (22q11;)." (PMID 26535572, 2015). "zDHHC8 in humans is encoded by the ZDHHC8 gene located on chromosome 22q11, a locus associated with susceptibility to schizophrenia." (PMID 26535572, 2015). "Splice variants of ZDHHC8 or changes in its expression level have also been shown to have a significant role in modulating the development of schizophrenia especially in individuals with 22q11 deletions." (PMID 19445674, 2009). "Recently, Mukai and colleagues proposed a gender-specific effect of the ZDHHC8 gene at 22q11 to liability to schizophrenia based on animal models followed by human association studies." (PMID 16225675, 2005). "A recent study revealed an elevated expression of zDHHC8 in the brain tissue of patients suffering from temporal lobe epilepsy, and there is also a possible (although still controversial) association between ZDHHC8 polymorphism and schizophrenia." (PMID 36087837, 2022). "Interestingly, PRODH and ZDHHC8 both have single nucleotide polymorphisms (SNPs) that are closely associated with 22q11DS-related schizophrenia-like symptoms." (PMID 35457231, 2022). "For example, it has been found that a genetic variant of ZDHHC8 (a gene predisposing to schizophrenia) is causally related to a reduction in the strength of synaptic connections and alterations in the terminal arborisation of both cortical and hippocampal neurons." (PMID 35457231, 2022). "DHHC8 has increased expression in epilepsy patients, and single-nucleotide polymorphisms (SNPs) in the zDHHC8 gene are associated with susceptibility to schizophrenia." (PMID 33981723, 2021). "Two closely related PATs, ZDHHC5 and ZDHHC8, have been associated with schizophrenia." (PMID 34659801, 2021). "Also, Zdhhc8-deficient mice display similar dendritic and synaptic changes and schizophrenia-like phenotypes." (PMID 34659801, 2021). "As a result of this rearrangement, the Rtn4r mouse gene is located between the Prodh gene (∼40-kb proximal) and the Zdhhc8 gene (∼70-kb distal), both of which have been implicated by human genetic studies as strong candidate susceptibility genes for schizophrenia." (PMID 18043741, 2007). "Recently, the gene ZDHHC8 encoding a putative palmitoyltransferase at 22q11 was proposed to increase liability to schizophrenia based on both animal models and human association studies by significant over-transmission of allele rs175174A in female, but not male subjects with schizophrenia." (PMID 16225675, 2005). "The functional variants could locate within ZDHHC8 or other genes around this locus at 22q11 and may independently or synergistically exert increased risk for schizophrenia." (PMID 16225675, 2005). "It has also been found that the effects of ZDHHC8 are at least partially mediated by the Cdc42-dependent modulation of Akt/Gsk3b signalling, which is consistent with the increasingly supported association between dysregulated Akt/Cdc42 signalling dysregulation and schizophrenia in humans." (PMID 35457231, 2022). "We next investigated the effects of cLTP on the post-translational regulation of ZDHHC8, which has a role in synaptic development and was found to be disrupted in a subset of patients with schizophrenia." (PMID 37039765, 2023).
schizophrenia (continued). "Among the top 40 genes associated with developmental delay, DGCR6, PRODH, DGCR5, and ZDHHC8 are potential candidates for involvement in DiGeorge syndrome pathology and schizophrenia." (PMID 37486921, 2023). "One interesting protein identified as abundant and proximal to all three family members is ZDHHC8, a palmitoyltransferase with disease connections to schizophrenia." (PMID 35487243, 2022). "Among the top candidate genes pinpointed by the analysis of the link between neuronal RG differentiation and schizophrenia are ZDHHC8, NCOR2 and CACNA1A, which were previously implicated as SCZ risk genes." (PMID 34194671, 2021). "Systematic meta-analysis on the psychotic diseases including schizophrenia, BAD, and ADHD identified several gene variants in ZNF804A, the zinc finger DHHC-type-containing 8 (ZDHHC8) and the zinc finger with KRAB and SCAN domain 4 (ZKSCAN4) genes." (PMID 32117005, 2020). "In the same direction association studies have reported several genes of this region associated with risk to develop schizophrenia and bipolar disorder, including PRODH, COMT, ZNF74, PCQAP, UFD1L, ZDHHC8, DGCR2 and SNAP29." (PMID 18284679, 2008). "Zdhhc8 knockout mice had sexually dimorphic deficits in prepulse inhibition and other features proposed to mimic schizophrenia in mice." (PMID 16225675, 2005). "While ZDHHC8 has not been yet associated with BD, it has been related to schizophrenia and epilepsy overlapping with ANK3." (PMID 36969554, 2023). "We chose to further study ZDHHC2 and ZDHHC5 as they have been shown to regulate activity-induced palmitoylation of synaptic proteins, as well as ZDHHC8 and ZDHHC9 as their function is disrupted in a subset of patients with schizophrenia and X-linked intellectual disability, respectively." (PMID 37039765, 2023). "Zdhhc8 expression was particularly enriched in Layer 2/3 of the neonatal (not shown) and adult mouse cortex, which is the cortical layer with the most pronounced morphological deficits in patients with Schizophrenia." (PMID 35819139, 2022). "However, consistent with a role for ZDHHC8 in schizophrenia, 22q11-deletion mice have reduced dendritic growth, spine density, and glutamatergic synapses that can be rescued with exogenous expression of ZDHHC8." (PMID 34659801, 2021). "It is therefore of considerable interest that our data indicates that the D2R, a principal target of the antipsychotic drugs used to treat schizophrenia, may represent a substrate for palmitoylation by zDHHC8." (PMID 26535572, 2015). "Indeed, there are several other genes (e.g., ZDHHC8 and chimerin 2) that have been suggested to have a sexually dimorphic effect on the development of schizophrenia." (PMID 17134514, 2006). "The findings on rs175174 at ZDHHC8 are still far from being conclusive, but evidence for sexual dimorphism is moderate, and our data do not support a significant genetic contribution of rs175174 to the aetiopathogenesis of schizophrenia." (PMID 16225675, 2005). "Together, we found Zdhhc8 expression patterns in the mouse brain that are established early in postnatal development and maintained into adulthood, that also overlay with many brain regions and cell types that are known to be severely affected in patients with schizophrenia." (PMID 35819139, 2022). "Although ZDHHC8 is located on chromosome 22q11 and was initially identified as a potential candidate gene for schizophrenia, it turned out not to be involved in this disease in later studies." (PMID 32117005, 2020).
epilepsy (4 papers, 2018 to 2023). A brain disorder characterized by episodes of abnormally increased neuronal discharge resulting in transient episodes of sensory or motor neurological dysfunction, or psychic dysfunction. "We aimed to explore the association of ZDHHC8 with epilepsy and investigate its in epileptogenesis in in vivo and in vitro models through behavioral, electrophysiological, and pathological studies." (PMID 30038264, 2018). "zDHHC8 may be associated with epileptic seizures in humans, and knockdown of zDHHC8 may have anti-epileptogenic effects on drug-resistant epilepsy." (PMID 38293675, 2023). "We first found increased ZDHHC8 expression in the brains of temporal lobe epilepsy (TLE) patients, similar to that observed in chronic epileptic mice, strongly suggesting that ZDHHC8 is correlated with human epilepsy." (PMID 30038264, 2018). "These subjects are highly prone to seizure precipitation, suggesting that the ZDHHC8 may play a key role in human epilepsy." (PMID 30038264, 2018). "Our results indicate that ZDHHC8 may offer a new strategy for therapeutic interventions in epilepsy." (PMID 30038264, 2018). "Thus, ZDHHC8 may represent a major therapeutic target in epilepsy." (PMID 30038264, 2018).
22q11.2 deletion syndrome (2 papers, 2021 to 2023). 22q11.2 deletion syndrome (DS) is a chromosomal anomaly which causes a congenital malformation disorder whose common features include cardiac defects, palatal anomalies, facial dysmorphism, developmental delay and immune deficiency. "Several studies demonstrated that 22q11.2 deletion syndrome leads to spine density deficits and impaired dendritic growth, which can be modulated by ZDHHC8 activity." (PMID 33430908, 2021). "Consistently, overexpression of ZDHHC8 successfully restores spine density and stabilization in mice with 22q11.2 deletion syndrome to WT levels." (PMID 33430908, 2021).
glioma (2 papers, 2021 to 2024). A benign or malignant brain and spinal cord tumor that arises from glial cells (astrocytes, oligodendrocytes, ependymal cells). "For example, we constructed a lncRNA–miRNA–mRNA network to uncover the potential significance of Prostate Androgen-Regulated Transcript 1 (PART1)-hsa-mir-25-Talin 2 (TLN2)/Zinc Finger DHHC-Type Palmitoyltransferase 8 (ZDHHC8) in glioma." (PMID 39857625, 2024). "The interaction between PART1-hsa-mir-25-SLC12A5/TACC2/BSN/TLN2/ZDHHC8 is largely unclear in glioma and requires further analysis." (PMID 34660294, 2021). "SLC12A5/TACC2/BSN/TLN2/ZDHHC8 was downregulated in patients with glioma with poor OS." (PMID 34660294, 2021).
temporal lobe epilepsy (2 papers, 2018 to 2022). A localization-related (focal) form of epilepsy characterized by recurrent seizures that arise from foci within the temporal lobe, most commonly from its mesial aspect. "Therefore, we first examined ZDHHC8 expression and localization in the epileptogenic brain tissues of temporal lobe epilepsy (TLE) subjects and mice." (PMID 30038264, 2018).
X-linked intellectual disability (2 papers, 2023 to 2024). An X-linked intellectual deficiency in which not enough information is known, reported or published to indicate whether a gene causes non-syndromic or syndromic presentations. "For example, the functionally defective DHHC9 is related to X-linked intellectual disability and epilepsy and mutations in ZDHHC15 and ZDHHC8 are related to X-linked intellectual disability and schizophrenia, separately." (PMID 39598479, 2024).
autism spectrum disorder (1 paper, 2023). A spectrum of developmental disorders that includes autism, and Asperger syndrome. "For autism spectrum disorder, DGCR2, ARVCF, GNB1L, COMT, ZDHHC8, CHRNA7, and NRXN1 are candidate genes with various associated developmental defects." (PMID 37486921, 2023).
breast carcinoma (1 paper, 2022). "APOL3, APOL4, NR1H3, OSBPL1A, MAP2K6, and ZDHHC8 were protective genes for breast cancer prognosis." (PMID 35919504, 2022).
cervical cancer (1 paper, 2019). A primary or metastatic malignant neoplasm involving the cervix. "In renal and cervical cancer, high expression of ZDHHC8 is significantly correlated with shorter survival times, whereas in lung and pancreatic cancers high expression significantly correlates with longer survival rates." (PMID 30735487, 2019).
mesothelioma (1 paper, 2024). A usually malignant and aggressive neoplasm of the mesothelium which is often associated with exposure to asbestos. "zDHHC8 was implicated in mesothelioma, a cancer with poor prognosis due to its intrinsic radioresistance." (PMID 39429488, 2024). "zDHHC8 knockdown improved the benefits of X‐irradiation in mesothelioma cell lines, increasing apoptotic and micronucleic cells arrested in the G2/M checkpoint, and suppressed tumor growth, reduced cell proliferation, and promoted apoptosis in tumor‐bearing mice exposed to X‐irradiation." (PMID 39429488, 2024).
Parkinson disease (1 paper, 2022). A progressive degenerative disorder of the central nervous system characterized by loss of dopamine producing neurons in the substantia nigra and the presence of Lewy bodies in the substantia nigra and locus coeruleus. "In contrast, the projected-palmitoylome of DG granule cells which have the highest expression of Zdhhc21, Zdhhc4, Zdhhc24, and Zdhhc8 generated KEGG pathways related to ‘Ribosome’, ‘Cholinergic synapse’, and ‘Parkinson’s disease’." (PMID 35819139, 2022).
cancer (5 papers, 2019 to 2024). A tumor composed of atypical neoplastic, often pleomorphic cells that invade other tissues. "Based on the results of this study, we found a strong correlation between human ZDHHC8 expression and cancer survival." (PMID 38177255, 2024). "Admittedly, the relationship between hZDHHC8 and cancer progression is complex, because in some cases elevated ZDHHC8 expression correlates with poor prognosis, and in some cases it correlates with good prognosis." (PMID 30735487, 2019). "From publicly available data, we find that expression of human ZDHHC8 correlates significantly with cancer survival." (PMID 30735487, 2019). "Since ZDHHC8 has not been previously linked to these cancers we decided to study ZDHHC8 function, and whether it affects tissue growth or cell proliferation." (PMID 30735487, 2019). "Two representative DIRs are displayed here, which were downregulated (ZDHHC8) and upregulated (ZNF800) in five cancer types, respectively." (PMID 38067392, 2023).
tumor (4 papers, 2019 to 2024). "Over the past decades, studies have demonstrated that ZDHHC8 siRNA and X-irradiation significantly slowed tumor development in 211H tumor-bearing mice." (PMID 38177255, 2024).
ZDHHC8 also shares sentences with these, for which no sentence is quoted: epileptic seizures (2 papers); autism (1); bipolar disorder (1); depression (1); developmental delay (1); diseases of the larynx and vocal cords (1); pancreatic cancers (1); psychiatric disorder (1); type 1 diabetes (1).